ALB (albumin)
Diseases named in the same sentence as ALB in open-access papers (continued):
Sharing a sentence is not in itself a finding about the gene and the disease.
cancer (continued). "Nevertheless, the study noted the absence of clinical trials demonstrating that raising albumin levels, by means of intravenous infusion or hyperalimentation, decreases the excess risk of mortality in cancer patients, and by extension, patients with metastatic femoral fractures." (PMID 32245389, 2020). "The prognostic nutritional index (PNI), which is calculated from serum albumin level and lymphocyte counts, is one parameters that reflects preoperative nutritional status and has also been validated as an effective prognostic factor in various cancers, including UTUC 12,13." (PMID 32913461, 2020). "On the other hand, the present study has important clinical implications, since several groups of patients, including cancer patients, have impaired albumin levels, which in turn could determine both treatment efficacy and the adverse effects including drug-related toxicity." (PMID 31554226, 2019). "Interestingly, albumin nanoparticles of Paclitaxel, when intravenously administered, may improve the targeting variability by increasing the delivery to the cancer cells." (PMID 31394747, 2019). "Furthermore, the serum albumin level can be affected by cancer and cancer treatment." (PMID 30764845, 2019). "Interestingly, a percentage of ingested albumin may also enter some cancer cells through a receptor-mediated endocytic route rather than through macropinocytosis." (PMID 30967004, 2019). "In this study, we verified that the maternal diet could be an alternative to minimise the cancer-induced damage in adult offspring rats, such as an improvement in triglyceride levels and the albumin-to-globulin ratio, which were improved by maternal leucine as supplementation." (PMID 31200474, 2019). "This evidence was supported by detecting caveolin-1 (a key player in caveolae formation) over-expression in the cancer cells, and hypothesizing that an active transport (similar to albumin transcytosis in endothelial cells) is active directly within the spheroids’ mass." (PMID 31195727, 2019). "Therefore, serum albumin levels are useful prognostic factors in malignant tumors." (PMID 31070304, 2019). "Second, patients with elevated BMI tended to have an earlier cancer stage, relatively low energy expenditure due to the earlier cancer stage, and higher preoperative albumin level, indicating that such patients may have better nutrition and tolerance of surgery." (PMID 29751759, 2018). "Therefore, we speculate that co-delivery of the PTX and the VE with the VE-Albumin core-shell nanoparticles could improve the therapeutic efficiency of PTX against MDR cancers." (PMID 30366367, 2018). "Therefore, human serum albumin, the important plasma protein produced by the liver with a number of accepted clinical indications in chronic liver disease, would be a clinically important indicator for prognosis prediction in non-cancer cirrhotic patients." (PMID 30240398, 2018). "Cancer-related inflammation has been termed the 7th hallmark of cancer, and the systemic inflammatory response (SIR) measured using cellular (whole white cell counts, neutrophils, lymphocytes, and platelets) and humoral [C-reactive protein (CRP) and albumin] components." (PMID 29234999, 2018). "Also, the rate of albumin uptake could account for the difference in the effect of IT-139 on GRP78 in highly metabolic cancer cells (including HUVECS) compared to normal cells." (PMID 30038714, 2018). "Importantly, it has been shown that 20 % of an injected dose of a radio‐labelled albumin accumulates in rats bearing tumours (5 % of the total body weight), after 24 h,22 suggesting that rHSA could be used for cancer targeted drug‐delivery." (PMID 29729206, 2018). "However, when this reservoir of albumin thiols becomes depleted in a cancer state, ROS may accumulate within neutrophils leading to NETosis and seeding of hematogenous metastases." (PMID 30504805, 2018).
cancer (continued). "We exploited the ability of clinically safe EB to bind with endogenous albumin and to concentrate within LNs, and we engineered AlbiVax by conjugating EB derivatives with molecular vaccines to efficiently co-deliver adjuvant and peptide Ags into LNs for combination cancer immunotherapy." (PMID 29203865, 2017). "Therefore, a reduced albumin level may diminish the response of cancer patients to treatment and indicates poor survival." (PMID 28548947, 2017). "Besides, the CAR, which consists of serum CRP and serum albumin, may indicate not only inflammatory condition but also nutritional status of cancer patients." (PMID 27823974, 2017). "Finally, albumin availability for cancer tissues can be altered depending on individual EOC patients, as it could be associated with different plasma albumin levels." (PMID 28417928, 2017). "Higher serum albumin may exert an anticancer effect by stabilizing the circulating levels of growth factors, anabolic hormones, inflammatory cytokines and oxidative stress markers, which are considered to play important roles in cancer progression." (PMID 27399281, 2016). "Indeed, lower albumin levels correlate with poor survival of cancer patients." (PMID 27765916, 2016). "As a major element of serum total protein, albumin may affect cancer through several mechanisms." (PMID 26681341, 2015). "Markers of the systemic inflammatory response, including C-reactive protein and albumin (combined to form the modified Glasgow Prognostic Score), as well as neutrophil, lymphocyte and platelet counts have been shown to be prognostic of survival in patients with cancer." (PMID 25730322, 2015). "Therefore, pre-treatment serum albumin levels are useful prognostic indicators in cancer." (PMID 26356222, 2015). "Albumin may help to stabilize cell growth and DNA replication, buffer a variety of biochemical changes, and maintain sex hormone homeostasis to protect against cancers." (PMID 26585371, 2015). "Taken together, serum albumin could be deemed a good indicator of cancer survival." (PMID 22559838, 2012). "Furthermore, when samples taken following a diagnosis of cancer were compared with those taken before a diagnosis of cancer the proportion of cases with albumin (⩾35 g l−1, 74 vs 81%) adjusted calcium (>2.60 mmol l−1, 3 vs 5%), Alk phos (>280 U l−1, 15 vs 18%), ALT (⩾50 U l−1, 10 vs 11%)." (PMID 20717110, 2010). "On multivariate analysis of these significant covariates, albumin (HR 4.77, 95% CI 1.35–16.85, P=0.015), locoregional treatment (HR 3.64, 95% CI 1.04–12.72, P=0.043) and systemic treatment (HR 2.29, 95% CI 1.23–4.27, P=0.009) were significant independent predictors of cancer-specific survival." (PMID 18797461, 2008). "The C-reactive protein-albumin-lymphocyte (CALLY) index reflects nutritional, immune, and inflammatory status and has shown prognostic value in other cancers." (PMID 41816341, 2026). "Their spectral and photophysical properties, interactions with bovine serum albumin, subcellular localization, and in vitro PDT efficacy in three human cancer cell lines were assessed." (PMID 41649332, 2026). "The C-reactive protein-albumin-lymphocyte (CALLY) index reflects the body's inflammatory, nutritional, and immune status, and has been shown to correlate with cancer prognosis." (PMID 42175397, 2026). "Besides the use of small albumin binders known to extend serum half-life, specific combination therapies with small constructs may provide an alternative solution together with significant advantages for cancer treatment." (PMID 41199882, 2025). "In response to the exacerbation, progression, and metastasis of inflammation in cancer tissues, the CRP concentration increases, whereas that of albumin decreases." (PMID 40144575, 2025). "The NPS, which integrates albumin levels, total cholesterol, NLR, and LMR, was originally designed to assess cancer-related outcomes but has gained attraction in cardiovascular research." (PMID 40283491, 2025).
cancer (continued). "In clinical applications, nanoparticle albumin-conjugated paclitaxel (nab-paclitaxel, nab-PTX) has been successfully used for targeted therapy of KRAS-mutant cancers (e.g., pancreatic cancer and breast cancer)." (PMID 40723808, 2025). "By integrating NLR with BMI and albumin levels, ALI simultaneously evaluates both the inflammatory response and nutritional status, two critical determinants of cancer progression and prognosis." (PMID 40535131, 2025). "The first model (M1) included clinicopathological factors such as region, ECOG status, number of metastatic sites (extent of cancer), BMI, treatment, NLR, LDH, albumin, and CA 19–9." (PMID 40956377, 2025). "Among cancer patients presenting with either symptom, 73-81% had one or more APR blood tests (platelet, inflammatory marker, white blood cell (WBC), ferritin, albumin) in the year before diagnosis." (PMID 39799273, 2025). "Previous studies have shown that dysregulation of BLC2, ALB, and STAT3 plays a significant role in cancer-related fatigue by driving systemic inflammation and metabolic alterations." (PMID 40435272, 2025). "The findings of this meta-analysis underscore the potential utility of the lactate dehydrogenase-to-albumin ratio (LAR) as a simple, cost-effective, and readily available prognostic biomarker across various cancers." (PMID 40693202, 2025). "The intersection of these methods yielded the final 12 variables: age, albumin, BUN, CRRT, GCS, lactate, mechanical ventilation, malignant tumor, PTT, platelet count, RDW, and vasopressor use." (PMID 40692680, 2025). "Another solution to presented problem may be adding albumin to the treatment regimen, as it appears to be able to increase the binding of drug to albumin, therefore to increase half-life of circulating drug and its entry into cancer cells, making it useful way to modify treatment." (PMID 40051558, 2025). "In the adjusted model for hospitalization‐free survival for both NLR and albumin, CTLA‐4 checkpoint therapy, ECOG > 0 and cancer stage IV were the significant predictors of hospitalization." (PMID 39817619, 2025). "Several biomarkers have been proposed to predict the outcomes of cancer cachexia, including inflammatory markers such as C‐reactive protein (CRP), lymphocyte‐to‐CRP ratio (LCR) and the CRP‐to‐albumin ratio (CAR)." (PMID 41216846, 2025). "The established relationship between high levels of albumin or AGR and favorable prognosis in cancer patients is well-established." (PMID 39917166, 2025). "Some of these factors, such as the gut microbiome, or serum albumin level, have been shown to correlate with ICI outcomes in various cancer types." (PMID 40075562, 2025). "Several studies have demonstrated that albumin nanoparticle internalization in HEK293 cells occurs via a SPARC-dependent pathway, with uptake levels comparable to those observed in cancer cells (~75% as measured by confocal microscopy and flow cytometry)." (PMID 41373713, 2025). "NPS takes into account ALB, TC, NLR and LMR, all of which have previously demonstrated correlations with outcomes in various cancer types." (PMID 40018412, 2025). "Of the 18 variables collected from the electronic medical records, age, sex, BMI, cancer presence, WBC, RBC, serum albumin levels, AST, ALT, ALP, and CRP were included as covariates for propensity score matching." (PMID 39881383, 2025). "With the simple measurement of serum albumin concentration and body weight, the Geriatric GNRI can effectively serve as a reliable indicator of nutritional status, particularly in cancer patients and elderly populations." (PMID 39979915, 2025). "Paclitaxel bound to albumin has demonstrated increased OS, PFS, and ORR in cancers, such as NSCLC and pancreatic cancer." (PMID 40697515, 2025).
cancer (continued). "Decreased NAPPs, such as albumin and PON-1, can be attributed to different mechanisms: albumin synthesis is downregulated as the liver prioritizes acute phase protein production, and its reduction may be further exacerbated by cancer-associated cachexia development." (PMID 40559770, 2025). "Serum protein components, including albumin (ALB) and globulin (GLB), are widely used to evaluate the nutritional status and disease severity of cancer patients." (PMID 39917166, 2025). "Based on computed tomography images at the time of initial cancer cachexia diagnosis to calculate the L3-SMI, the CXI was calculated using serum albumin (ALB) level, neutrophil-to-lymphocyte ratio (NLR), and skeletal muscle index (SMI)." (PMID 41586248, 2025). "Within this study, the most frequent abnormal biomarkers among cancer patients were high inflammatory markers (CRP or ESR), low Hb, low albumin, low lymphocyte count and high ALP." (PMID 41371732, 2025). "The C-reactive protein (CRP)–albumin–lymphocyte (CALLY) index, an immunonutritional index, has shown prognostic value in various cancers." (PMID 40091005, 2025). "mGPS is based on CRP and albumin levels, and a serum CRP concentration greater than 10 ng/mL is an important indicator of the prognosis of cancer or chronic disease." (PMID 40672827, 2025). "Our study identified core genes (ALB, BCL2, EGFR, IL-6, and STAT3) enriched in cancer pathways, suggesting a potential link between cancer-related metabolic dysregulation and fatigue." (PMID 40435272, 2025). "The neutrophil-to-albumin ratio (NPAR), a novel marker of systemic inflammation, has been utilized to predict outcomes in patients with cancer and cardiovascular diseases." (PMID 40697910, 2025). "TheCAR was first evaluated in patients with cancer, surgical patients and criticalillnesses and was found to have better predictive value than CRP or ALB alone foradverse outcomes." (PMID 39742221, 2024). "We observed differential expression of four genes, ALB, KIT, PDGFRB, and TGFBR1, in regular and neighbouring cancer tissues." (PMID 39364054, 2024). "Combining these latter aspects (weight loss, BMI, SGA and serum albumin levels) suggested that the Nutritional Risk Index (NRI) could represent an index to predict good or bad prognosis in patients undergoing chemotherapy, even if future validation of specific tests for cancer patients is needed." (PMID 39062127, 2024). "Combined indices such as the AGR and CAR, which emphasize combinations of markers that directly reflect the cancer–nutrition relationship, including CRP, albumin, and globulin, have also been investigated in GBM." (PMID 39330000, 2024). "Our study examined the relationship between ALB and ALP levels using a representative sample of United States patients with cancer that were enrolled in NHANES 2011 to 2018." (PMID 38552093, 2024). "May be related to cancer of the liver patient’s own accelerate protein decomposition, synthesis, exogenous albumin supplementation does not effectively maintain blood albumin levels, so in this case the input albumin to improve the prognosis of confirmed that need to be studied further." (PMID 39039452, 2024). "The C-reactive protein-albumin-lymphocyte (CALLY) index has been identified as a useful and sensitive predictive tool for stratification in cancers." (PMID 38184747, 2024). "The albumin-nanoparticle-wrapped PTX is internalized through active macropinocytosis, resulting in the inhibition of cancer cells’ growth." (PMID 39000072, 2024). "Prealbumin, albumin, and C-reactive protein (CRP) levels and the upper arm muscle area (UAMA) were measured before and after treatment in children with cancer and compared with the control group to evaluate nutritional status." (PMID 39619813, 2024).
cancer (continued). "The study suggested that cyclic RGD-functionalized closo-dodecaborate albumin conjugates have the potential to serve as an effective boron carrier for BNCT, providing improved targeting and therapeutic efficacy for cancer patients." (PMID 38961887, 2024). "A recent pan-cancer study indicated that in SCLC, patients with elevated albumin levels had improved response and survival outcomes with ICI treatment." (PMID 38911864, 2024). "Consequently, albumin levels emerge as a biologically plausible biomarker that can simultaneously indicate the nutritional and inflammatory status of cancer patients, in whom lower albumin levels may signal a more progressed cancer stage and a poorer prognosis." (PMID 39195131, 2024). "The hemoglobin, albumin, lymphocyte, and platelet (HALP) score is a prognostic marker in several types of malignant tumors." (PMID 38879594, 2024). "Other scores that aim to predict the outcome of cancer patients like the (modified) Glasgow prognostic score (m)GPS, that is based on simple, readily available blood parameters CRP and albumin, are only validated to assess survival probability at baseline." (PMID 39414641, 2024). "Ultimately, we arrived at a subset of five variables – Albumin, BUN, Cancer, Altered Mental Status, and Pulse – which were consistently selected by all five methods as well as our scoring system." (PMID 38902633, 2024). "Nevertheless, in the routine diagnostics of cancer patients the subjective tools (SGA, NRS questionnaires), anthropometric measurements and laboratory parameters (albumin, CRP) are constantly used." (PMID 38790185, 2024). "This was particularly driven by patients with rapid clinical progression (clinical PD (cPD)) having significantly lower albumin and higher NLR, both responses to inflammation shown to be strongly prognostic across cancer types and treatment settings." (PMID 38429524, 2024). "In clinical settings, the C-reactive protein (CRP)-to-albumin ratio (CAR) has been investigated as a prognostic marker for diverse diseases, including cancer." (PMID 39330000, 2024). "In LIHC, ALB, a novel potential driver gene predicted by PDRWH, has been proposed as an effective biomarker for cancer detection." (PMID 38683860, 2024). "Several inflammatory biomarkers and nutritional indicators, such as the neutrophil-to-albumin ratio (NAR) and the combined index of hemoglobin, albumin, lymphocytes, and platelets (HALP), correlate with prognosis in many cancers." (PMID 39026969, 2024). "Recently, the Fibrinogen–Albumin-Ratio Index (FARI), which considers both fibrinogen and albumin levels, was proposed as a novel prognostic biomarker in several cancer types." (PMID 39409916, 2024). "In univariate and multivariate analyses, predictors of death among cancer patients were male sex, older age, presence of dyspnea, elevated troponin, elevated AST (0.001) and ALT (0.05), low albumin (p=0.04) and mechanical ventilation (p=0.001)." (PMID 38633403, 2024). "Although it is well known that low albumin levels and PNI scores serve as prognostic predictors for overall survival rates, studies focusing on cancer survivors with LLL are rare." (PMID 39529928, 2024). "Performance status (PS), albumin levels, C-reactive protein (CRP), and body mass index (BMI) correlate with survival outcomes across cancer types." (PMID 39330032, 2024). "The LDH–albumin ratio (LAR), along with the albumin- and lymphocyte-based prognostic nutritional index (PNI), has been researched in various cancers and acknowledged as a significant prognostic indicator." (PMID 39597034, 2024). "The NUn score, which incorporates CRP and ALB levels and WBC counts, effectively captures the key aspects of systemic inflammation and nutritional status, which are both critical determinants of cancer progression and patient outcomes." (PMID 39513125, 2024).